CCR7 (C-C motif chemokine receptor 7)
Diseases named in the same sentence as CCR7 in open-access papers (continued):
Sharing a sentence is not in itself a finding about the gene and the disease.
colitis (23 papers, 2008 to 2025). Inflammation of the colon. "In this study, we investigated whether CCR7 deficiency resulted in failure of immune suppression in 2% dextran sulfate sodium-induced colitis." (PMID 26908454, 2016). "Here, we investigated if CCR7 deficiency aggravates DSS-induced colitis." (PMID 26908454, 2016). "Here, we investigated whether CCR7 deficiency leads to severe intestinal inflammation in a murine dextran sulfate sodium (DSS)-induced colitis model." (PMID 26908454, 2016). "The CCR7-deficient mice or mice treated with anti-CCR7 mAb develop an exacerbated ileo-colitis, which is associated with retention of Th effectors in intestinal and extra-intestinal tissues, suggesting that recirculation of CCR7+ TEM contribute to intestinal homeostasis." (PMID 26284078, 2015). "Ozanimod was shown to induce the internalization and degradation of these receptors, improve the histological score in mice with TNBS (and adoptive CD4+CD45RB+T-cell transfer mediated) colitis and reduce the numbers of circulating B and CCR7+ T-lymphocytes." (PMID 35163775, 2022). "Meanwhile, the correlation analysis showed that Alistipes was negatively correlated with MPO and CD4+CD45+CCR7+ and CD4+CD45+CCR7+ cells when experimental colitis was treated with COG." (PMID 35832382, 2022). "Concomitant with colitis development, DCs in inflamed patients increase in number and upregulate the expression of CCR7, TNF, and CXCR3 costimulator molecules." (PMID 35813827, 2022). "Loss of CCR7 and CCR4impairs the functions of Tregs in experimental colitis, and further CCR7 regulates the balance between Th1, Th17, and Trges in Crohn’s-like Murine ileitis." (PMID 34440615, 2021). "The number of CD45RA−CD62L+CCR7+ cells (Figures2C1–5) was dramatically reduced in the untreated colitis mice in contrast to the normal mice." (PMID 32714185, 2020). "In this study, we evaluated whether cell percentages of CD4+CD45RA+CCR7+CXCR5+ (CD4+ mTfh) cells changed in experimental colitis." (PMID 35388299, 2022). "cDC1s have been shown to express DC-specific transcription factors, migrate to MLNs in a CCR7 dependent manner, and interact with CECs to limit colitis pathlogy, yet little is known about how epigenetic processes may regulate their function." (PMID 32117307, 2020). "PGE2 is known to be crucial for immune responses, such as by increasing CCR7-driven DC migration and homing to draining lymph nodes, efficient T cell activation, keeping the gut mucosal barrier intact against colitis, and homeostasis." (PMID 29850633, 2018). "Interestingly, CCR7 deficiency resulted in a higher percentage of pDCs as compared to that in the WT mice, in the DSS-induced colitis model." (PMID 26908454, 2016). "Observations that P3 iMPs can up-regulate CCR7 suggest that they could contribute to colitis by initiating a harmful T cell response in draining lymph nodes and/or stimulating effector T cells in the LP." (PMID 26121642, 2015). "CCR7 deficient mice develop diarrhea autoimmune gastritis and exocrinopathy accompanied by the formation of mucosal tertiary lymphoid follicle which causes diarrhea associated with altered ion transport in colonocytes in absence of overt colitis." (PMID 26908454, 2016). "In the present study, we also found that the colitis mice presented similar results with lower frequencies of mTreg (CD4+Foxp3+, CD4+CCR7+Foxp3+, CD4+CCR7−Foxp3+) cells and higher mTh17 (CD4+CCR6+, CD4+CCR7+CCR6+, CD4+CCR7−CCR6+) cells." (PMID 38202824, 2024). "As the two subsets of Tcm cells, CD4+CD45RA−CD62L+CCR7+ (Figures 2D1–5) and CD8+CD45RA−CD62L+CCR7+ (Figures 2E1–5) cells were downregulated after colitis mice were treated by SSP and 5-ASA for 7 days." (PMID 32714185, 2020). "In addition, DEGs associated with the immune receptor (Lrrc19), cell chemotaxis (Ccr7, Cxcl1, Cxcl5, Cxcl9, and Cxcl10), and inflammatory response (IL1r11, IL11, Tnf, IL1β, and IL18) were also upregulated in the colonic tissue of colitis mice in DVF group." (PMID 38172943, 2024).
colitis (continued). "In this study, CD4+CCR7+/− cells in mice with DSS-induced colitis were overactivated, and their subsets CD4+CCR7+IL-17A+ and CD4+CCR7−IL-17A+ increased significantly, while CD4+CCR7+IL-10+, CD4+CCR7−IL-10+, CD4+CCR7+Foxp3+, and CD4+CCR7−Foxp3+ decreased significantly." (PMID 35832382, 2022). "As for cell surface markers, such as CCR7, CD127, CD11c, and CD103 implicated in M1 macrophages and dendritic cells, both of which have been shown to play proinflammatory role in colitis were not expressed on either subpopulations within CD11b+ cells." (PMID 25254662, 2014). "In support of this idea, the Ly6Chi monocyte-derived MP that accumulate in the MLN during T cell transfer colitis lack CCR7 and this process occurs in the absence of CCR7." (PMID 24726741, 2014). "We found an increased CCR7 expression of MLN DC but not of LP DC in E. coli mpk mono-colonized mice prior to onset of colitis." (PMID 18545662, 2008). "Critically, the colitis mice also exhibited an abnormal imbalance of mTh17/mTreg cells with higher frequencies of CD4+CCR7+CCR6+ cmTh17 and CD4+CCR7−CCR6+ emTh17 cells and lower frequencies of CD4+CCR7+Foxp3+ cmTreg and CD4+CCR7−Foxp3+ emTreg cells in the MLNs." (PMID 38202824, 2024). "Notably, APS significantly down-regulated the percentages of Th17 (CD4+CCR6+), cmTh17 (CD4+CCR7+CCR6+) and emTh17 (CD4+CCR7−CCR6+) cells and significantly up-regulated the percentages of cmTreg (CD4+CCR7+Foxp3+) and emTreg (CD4+CCR7−Foxp3+) cells in the mesenteric lymph nodes of the colitis mice." (PMID 38202824, 2024). "Plasmacytoid dendritic cell numbers were also slightly increased during intestinal inflammation in the absence of CCR7, and the depletion of those cells exacerbated DSS-induced colitis in CCR7KO mice." (PMID 26908454, 2016). "Despite data showing that migration of LTi ILC3s from the gut to the mesenteric lymph nodes is dependent on CCR7 expression, expression of CCR7 on ILCs was not assessed in that study and we were unable to identify CCR7 or CCR2 on intestinal ILC3s in anti-CD40 induced colitis." (PMID 26780670, 2016). "Based on the attenuated colitis shown in DSS-treated CCR7KO mice, we verified whether migration of CD4+ Tregs into the lymph node was impaired in the absence of CCR7." (PMID 26908454, 2016).
leukemia (23 papers, 2011 to 2025). A malignant (clonal) hematologic disorder, involving hematopoietic stem cells and characterized by the presence of primitive or atypical myeloid or lymphoid cells in the bone marrow and the blood. "Other leukemias associated with CCR7 include chronic myelogenous leukemia (CML), which is characterized by the presence of the Philadelphia chromosome containing the BCR-ABL fusion gene." (PMID 35203305, 2022). "For B-CLL, CCR7-enhanced expression of MMP-9 was associated with increased migration of leukemia cells to lymph nodes and for non-Hodgkin’s lymphoma to an increase in cancerous lesions." (PMID 35203305, 2022). "However, AML cases with high SLAMF6 expression on the leukemia cells were found to have higher frequencies of CCR7+CD45RA+ T cells, an immunophenotype associated with naive cells." (PMID 41044242, 2025). "Mechanistically, mTORC2 acted through CCR7 and an Akt-dependent NF-κB pathway to modulate leukemia cell migration and survival." (PMID 35203305, 2022). "In T-ALL cells, CCL19 activation of CCR7 was sufficient to promote the entry of the leukemia cells into the CNS and for ALL patients, in general, ZAP70 was elevated along with CCR7 and CXCR4, which was also linked to CNS spread." (PMID 35203305, 2022). "In T-ALL, mTORC2 was shown, like CCR7, to be downstream in the Notch-1 signaling pathway that activated the Akt-dependent NF-κB pathway to modulate leukemia cell survival." (PMID 35203305, 2022). "Blocking CCR7 with a monoclonal antibody abrogated these tumor characteristics and led to leukemia cell death in vitro and in a xenograft mouse model." (PMID 35203305, 2022). "In both types of leukemia, CCR7 was detected in a small proportion of tumorous NK-cells (<25%), a lower proportion than the relative number of CCR7-positive NK-cells the authors found in six healthy controls." (PMID 34778050, 2021). "Silencing of the CCR7 or its ligand CCL19 in animals models has been reported to inhibit infiltration of leukemia cells into the brain." (PMID 33414786, 2020). "In the central nervous system, CCR7 expression in the brain endothelial cells, is an essential adhesion signal for CCR7+ leukemia T-cells to specifically seed and metastasize to central nervous system." (PMID 33414786, 2020). "We found that leukemia cells expressed a basal level of CCR7, whereas expression of MIP-3β was undetectable, and co-culture of T-ALL cells with spleen cells increased the expression of both of these genes in leukemia cells." (PMID 25366136, 2014). "Overall, there is clear evidence that CCR7 plays important roles in leukemia migration." (PMID 35203305, 2022). "In leukemias, the expression of CCR7 is a significant prognostic factor." (PMID 33076281, 2020). "Many leukemia and lymphomas also express CCR7, and this may account for their tropism for lymph nodes (especially T-cell zones)." (PMID 29666622, 2018). "Identification of Ccr7 as a major target highlights the complementary value of RIM screening, as this gene does not appear to be subject to mutation or amplification in human cancer, yet is required for CNS metastasis of human leukaemia cells." (PMID 24586197, 2014). "By activating either the T-cell receptor for T-CLL or the B-cell receptor for B-CLL, CCR7 induced expression of the protein tyrosine kinase, ZAP70, increasing leukemia cell actin polymerization and migration, suggesting an alternative CCR7-linked actin-dependent migratory pathway in leukemia." (PMID 35203305, 2022). "Six genes were identified in baboons (WNT3, POU2AF1, CCR7, ARG2, CD177, and WLS) and validated in human leukemia patients exposed to radiotherapy." (PMID 33737626, 2021). "The other ligand for CCR7, CCL21, was undetectable in mouse brain sections and presumed to be less important for leukemia migration into the CNS." (PMID 28491865, 2017). "Finally, altered expressions of CD28, CCR7, CX3CR1, IFNG, LTB and PRF1 were all contributing to the inflammatory profile of the TCRγδ+ T-LGL leukemias." (PMID 28407008, 2017).
leukemia (continued). "Interestingly, CCR7 that regulates CNS infiltration in T-ALL and CXCR4, which is essential for stem cell and leukemia cell localization were both repressed upon KLF4 overexpression in Jurkat cells." (PMID 25644173, 2015). "Nevertheless, the increased migration of the T-ALL leukemia cells to the spleen is owing to enhanced chemotaxis of T-ALL cells to spleen via the MIP-3β-CCR7 pathway, not just normal homing phenomenon." (PMID 25366136, 2014). "In addition, some leukemias, such as B cell chronic lymphocytic leukemia but not multiple myeloma cells, show CCR7 expression." (PMID 33076281, 2020). "Previous studies have demonstrated that several adhesion molecules and chemokines, including CXCR4, CD56, CD44, CCR7, and VLA-4, contribute to the harboring and proliferation of leukemic cells in the BM niche and may enhance niche-mediated resistance in leukemia." (PMID 22069486, 2011). "SELL, PTPRC, IL7R, CCR7, and KLRB1 were able to distinguish leukemia cells from normal cells well, with AUC values higher than 0.970." (PMID 38165493, 2024). "Eμ-Tcl1 Tg leukemias exhibited heterogeneous surface staining for CXCR4, CXCR5 and CCR7, but were negative for CXCR3." (PMID 27843137, 2017). "Human leukemia cells of myeloid origin, such as conventional, as well as differentiated and matured HL60 and THP1 cells, or MUTZ cells were tested, but none of these attempts succeeded in cells that expressed CCR7 and migrated towards its chemokine ligands." (PMID 34603281, 2021). "Silencing of CCR7 in leukemia cells, or one of its ligands CCL19 in mice, specifically diminished infiltration of the CNS, but not other tissues, in both murine and xenotransplantation leukemia models." (PMID 28491865, 2017).
Obesity (23 papers, 2011 to 2024). Accumulation of substantial excess body fat. "The CCL19/CCR7 pathway promotes the progression of high-fat-induced IR and obesity, and these issues are well-known as risk factors for accelerating the pathogenesis of NAFLD and AS." (PMID 37063958, 2023). "Ccr7, a chemokine receptor expressed in various immune cells and is linked to obesity as its knockout in mice results in protection from diet-induced obesity." (PMID 36653487, 2023). "The protein encoded by CCR7 has been shown in mice to play a causal role in maintaining innate and adaptive immunity contributing to adipose tissue inflammation in obesity." (PMID 35665255, 2022). "A recent study showed that infiltration of CCR7-expressing cells in adipose tissue is associated with insulin resistance in obesity." (PMID 33853536, 2021). "cDC accumulation during obesity has been shown to be attenuated in Ccr7−/− mice and associated with decreased adipose tissue inflammation and lowered fasting glucose and insulin levels, suggesting that DCs are only partially CCR7-dependent." (PMID 31191541, 2019). "Therefore, this study suggests that therapeutic administration of anti-CCR7 antibody is a feasible approach for treating obesity-associated metabolic diseases." (PMID 34421909, 2021). "In Ccr7 null mice, browning of white adipocytes as well as the activation of brown adipocytes cause enhanced energy metabolism, resulting in protection against diet-induced obesity." (PMID 31312229, 2019). "We hypothesized that Ccr7 may play important role in browning process as loss of function of Ccr7 results in the suppression of the development of obesity and/or insulin resistance." (PMID 31312229, 2019). "Another study had a different opinion regarding the dependency of ATM accumulation on CCR7 in obesity." (PMID 34421909, 2021). "Primary examples include chemokine receptors (CXCR1, CXCR2, CXCR4, CCR5, CCR7) that drive chronic inflammatory responses common to both obesity and cancer." (PMID 33329395, 2020). "We have previously reported that ccr7 null mice were protected from diet-induced obesity and adipose tissue inflammation, and revealed an increase in brown adipocyte markers in the white adipose tissues." (PMID 32346618, 2020). "To confirm the infiltration of DARC+ monocytes under obesity conditions, we compared the frequency of CCR7+DARC+ or CD206+DARC+ subsets in the monocyte/macrophage populations in SVCs between WT and db/db mice." (PMID 31817755, 2019). "Notably, studies link obesity to the accumulation of CD11c+ immune cells expressing CCR7, contributing to chronic inflammation and insulin resistance." (PMID 38474155, 2024). "A study investigating the participation of IL-10 in an experimental model of steatosis suggested that CCR7+ mononuclear cells in the liver could regulate obesity-induced hepatic steatosis via the induction of IL-10-expressing invariant natural killer T cells." (PMID 37336969, 2023). "Considering the intersection with HFD, obesity can promote the accumulation of CCR7+ macrophages and dendritic cells in adipose tissue in close proximity to lymph nodes; however, in this model we were not able to co-localize IBA1 and CCR7 (in two different staining panels) to assess this." (PMID 37801190, 2023). "Additionally, a study has also shown that the pathway formed by the CCL19 gene and its receptor CCR7 plays a key role in inducing obesity and insulin resistance." (PMID 35812876, 2022). "CCR7–/– mice are protected from diet-induced obesity and subsequent insulin resistance, which may protect CCR7–/– mice from CAVD." (PMID 36684607, 2022). "We previously reported that Ccr7 null mice are protected from diet-induced obesity." (PMID 31312229, 2019). "Therefore, CCR7 is a potentially effective therapeutic target against obesity and/or related diseases." (PMID 31312229, 2019). "The lymphoid homing receptor, CCR7, was also increased in splenic Tregs in obesity." (PMID 21298111, 2011).
Obesity (continued). "During obesity, ATDC migration tracking has been studied using Ccr7−/− mice, as ATDC migration is specifically dependent on CCR7 but independent of CCR2, whereas monocyte-derived ATMs are dependent on CCR2." (PMID 34445379, 2021). "In addition, HFD-induced ATM accumulation in monocytes is dependent on CCR2, whereas AT-DC accumulation is less dependent on CCR2 but more dependent on CCR7, suggesting that AT-DCs play an independent role in VAT inflammation during obesity." (PMID 34421909, 2021). "Mice lacking Ccr7 are protected from diet-induced obesity and subsequent insulin resistance." (PMID 31312229, 2019). "Finally, mice lacking CCR7 are protected from diet-induced obesity and insulin resistance." (PMID 37296834, 2023). "Furthermore, mice lacking Ccr7 are protected from diet-induced obesity." (PMID 31312229, 2019). "Together, these data suggest that CCR7 plays a role in CD8+ATT cell egress, but does not influence ATM accumulation or the metabolic impact of diet‐induced obesity." (PMID 27655794, 2016). "In addition, a study used Ccr7−/− mice, where lack of ATDCs was observed during lean and obese and demonstrated failure of ATM accumulation under obesity." (PMID 34445379, 2021). "Interestingly, Ccr7−/− mice exposed to HFD did not suffer ATDC accumulation in VAT followed by protection to AT inflammation and insulin resistance, indicating the important participation of ATDC migration in early stages of obesity." (PMID 34445379, 2021).